CRY1 (cryptochrome circadian regulator 1)
Diseases named in the same sentence as CRY1 in open-access papers (continued):
Sharing a sentence is not in itself a finding about the gene and the disease.
Cognitive impairment (2 papers, 2021 to 2023). Abnormal cognition is characterized by deficits in thinking, reasoning, or remembering. "Sleep-dependent memory was severely compromised in SCNCon mice, consistent with other reports of cognitive impairment in Cry1/Cry2-nulls." (PMID 34446572, 2021). "In addition, as it was a cross-sectional study, we could not explain the causal relationship and specific mechanism between the promoter methylation of PER1, CRY1 and cognitive impairment in CSVD patients." (PMID 37293664, 2023).
colorectal tumor (2 papers, 2013 to 2016). "Our future studies will be aimed to more fully dissect the molecular mechanism underlying Cry1 promotion of colorectal tumor cell growth,migration and the progression of CRC." (PMID 23626715, 2013). "The same results were found in colorectal tumor cells and normal cells, and overexpression of Cry1 was found to promote growth and migration in colorectal tumor cells." (PMID 23626715, 2013). "Interestingly, overexpression of another cryptochrome (cry1) in colorectal tumors correlates with metastasis formation." (PMID 26846883, 2016).
coronary artery disease (2 papers, 2015 to 2025). "In aorta, we identified perturbations in a number of TFs involved in circadian clock regulation (CRY1, CRY2, PER2), vascular inflammation (PPARG, NR3C1), and those linked in coronary artery disease, including the estrogen receptor, ESR2." (PMID 39896461, 2025).
liver disease (2 papers, 2024). "We also analyzed the GSE7400 and GSE38941 datasets, demonstrating that patients with liver disease have low expression of the hepatic Cry1 gene." (PMID 38822329, 2024). "In addition, analyses of gene-specific diurnal variations in levels of H3K27ac and H3K9ac of liver disease-driving genes (XBP1 and RAF1) and CC-component CRY1 confirmed the HCV-induced epigenetic perturbations." (PMID 39209804, 2024).
lymphoma (2 papers, 2016 to 2021). A malignant (clonal) proliferation of B- lymphocytes or T- lymphocytes which involves the lymph nodes, bone marrow and/or extranodal sites. "Previous studies demonstrated that mutation or knock out of clock genes Per2, Cry1/Cry2 or Bmal1 also accelerated the development of lymphomas following whole body exposure to γ radiations." (PMID 27494874, 2016).
renal carcinoma (2 papers, 2014 to 2021). A carcinoma arising from the epithelium of the renal parenchyma or the renal pelvis. "Furthermore, all renal cancer cell lines expressed CRY1 protein, but did not express PER2 protein." (PMID 25333958, 2014). "All renal cancer cell lines expressed CLOCK and CRY1 protein, but did not express PER2 protein." (PMID 25333958, 2014).
sarcoma (2 papers, 2021 to 2024). A usually aggressive malignant neoplasm of the soft tissue or bone. "In comparison to the only other analyses of CRY1 function in humans, CRY1 appears to harbor distinct activities in carcinomas versus sarcomas." (PMID 33452241, 2021).
septic shock (2 papers, 2021 to 2025). Shock caused by infection; frequently caused by gram negative bacteria, although some cases have been caused by other bacteria, viruses, fungi, and protozoa; characterized by fever, chills, tachycardia, tachypnea, and hypotension. "The rhythmicity of Bmal1, Per1/2, Cry1, Rev-Erb-α, and Rev-Erb-β in whole-blood is lost in patients with sepsis or septic shock, likely reflecting the changes in immune cells." (PMID 39968295, 2025). "Moreover, absolute levels of Cry1 and Rev-Erb-α/β transcripts were reduced, and Cry2 transcript was increased in the whole-blood of patients with septic shock." (PMID 39968295, 2025). "While CRY1, NR1D1, NR1D2, DBP, PER2 were suppressed in septic shock patients, CRY2, surprisingly was significantly upregulated compared to healthy young men." (PMID 33900485, 2021). "In addition, the expression of the clock genes CRY1, NR1D1, NR1D2, DBP, and PER2 were suppressed in septic shock patients, whereas CRY2 was significantly upregulated compared to healthy young men." (PMID 33900485, 2021).
Sleep apnea (2 papers, 2022 to 2023). An intermittent cessation of airflow at the mouth and nose during sleep is known as sleep apnea. "However, whether a similar mutation of the CRY1 gene can be found in PE patients with sleep-disordered breathing and subsequently cause the change of CRY1 transcript in placenta remains unclear." (PMID 36284122, 2022).
acute liver failure (1 paper, 2024). Rapid deterioration of liver function causing encephalopathy and coagulopathy. "Using the gene expression omnibus (GEO) database, we verified that Cry1 gene expression was also decreased in patients with APAP-induced acute liver failure." (PMID 38822329, 2024).
acute myocardial infarction (1 paper, 2021). Necrosis of the myocardium, as a result of interruption of the blood supply to the area. "CRY1 is a human circadian clock gene; and acute myocardial infarction and arrythmias are regulated by circadian clock genes." (PMID 33810615, 2021).
alcohol use disorder (1 paper, 2022). "Clinical investigations report reduced baseline Clock mRNA levels in patients with alcohol use disorder, as well reduced baseline mRNA levels of circadian proteins BMAL1, Per1, Per2, Cry1, and Cry2." (PMID 35456507, 2022).
Alzheimer disease (1 paper, 2021). A progressive, neurodegenerative disease characterized by loss of function and death of nerve cells in several areas of the brain leading to loss of cognitive function such as memory and language. "Similarly, the rhythmic expression of specific sleep genes (BMAL1, CRY1, and PER1) is also found to be disturbed in neurodegenerations such as mild cognitive impairment (MCI) and Alzheimer’s disease (AD) dementia." (PMID 35052403, 2021).
Arrhythmia (1 paper, 2020). Any cardiac rhythm other than the normal sinus rhythm. "Under constant blue light, cry1 plants have a greatly reduced amplitude, with rhythms of CCA1 and GI transcript accumulation trending towards arrhythmia." (PMID 31410859, 2020).
asthma (1 paper, 2025). "High expression of CRY1 was enriched in the arginine and proline metabolism pathways, whereas low expression was enriched in the asthma pathway." (PMID 40441253, 2025).
atopic dermatitis (1 paper, 2023). "CC3, characterized by high expression of BMAL1 and CRY1, had a low prevalence of atopic dermatitis, which is associated with decreased activation of cytokine–cytokine receptor interaction pathways." (PMID 37108640, 2023).
B-cell acute lymphoblastic leukemia (1 paper, 2012). A neoplasm of lymphoblasts committed to the B-cell lineage, typically composed of small to medium-sized blast cells. "We also compared the CRY1 expression in CLL with other lymphoid malignancies and observed epigenetic silencing of CRY1 in a patient with B cell acute lymphoblastic leukemia (B-ALL)." (PMID 22470559, 2012).
blood pressure (1 paper, 2023). "A large sample study that is part of a national health survey in the adult-aged ≥ 30 years showed that the CRY1 genetic variants have a role in elevated blood pressure and high triglyceride." (PMID 37580741, 2023).
Cachexia (1 paper, 2014). Severe weight loss, wasting of muscle, loss of appetite, and general debility related to a chronic disease. "We observed reduced amplitudes in the mRNA expression of Reverbα Per2, Pparγ C/ebpα, and associated genes (Fas, Lpl, Scd1, Dgat2) and a parallel increase in Bmal1, Cry1, Pbe and Tfam indicating alterations in the core clock regulation and lipid homeostasis during cachexia." (PMID 24667661, 2014).
chronic obstructive pulmonary disease (1 paper, 2025). A chronic and progressive lung disorder characterized by the loss of elasticity of the bronchial tree and the air sacs, destruction of the air sacs wall, thickening of the bronchial wall, and mucous accumulation in the bronchial tree. "The same study observed that the mRNA and protein levels of BMAL1, PER2, CRY1, and REV-ERBα were reduced in the peripheral blood mononuclear cells (PBMCs), lung tissue, and sputum cells of smokers and patients with chronic obstructive pulmonary disease (COPD) compared to non-smokers." (PMID 40255337, 2025).
clear cell carcinoma (1 paper, 2024). "Additionally, we confirmed that the olaparib treatment increased CRY1 and the phosphorylation of AKT, which was suppressed by the bevacizumab treatment, using another clear cell carcinoma cell line, OVTOKO." (PMID 38420012, 2024).
colon adenocarcinoma (1 paper, 2021). "Compared to normal skin, patients with skin cutaneous melanoma (SKCM) present significant down-regulation in the expression of BMAL1, CRY1, CRY2, PER1, PER2, and PER3, and higher expression of CLOCK, a similar pattern was also observed in patients with colon adenocarcinoma (COAD)." (PMID 34966277, 2021).
delirium (1 paper, 2022). A disorder characterized by confusion; inattentiveness; disorientation; illusions; hallucinations; agitation; and in some instances autonomic nervous system overactivity. "Delirium resulted in overall disruption of core clock genes in mouse hippocampus, including E4bp4, Bmal1, Rev‐erbα, Cry1, and Per2." (PMID 35713240, 2022).
dementia (1 paper, 2023). Loss of intellectual abilities interfering with an individual's social and occupational functions. "Furthermore, a previous study showed that abnormal methylation in circadian genes such as CRY1 and PER1 leads to dementia symptoms." (PMID 37388929, 2023).
dysthymia (1 paper, 2013). "This difference could explain why CRY2, not CRY1, associated with dysthymia in our study." (PMID 23951166, 2013).
endometrial cancer (1 paper, 2014). Primary or metastatic malignant neoplasm involving the endometrium (mucous membrane that lines the endometrial cavity). "Deregulated CRY1 expression has also been observed in CML and HNSCC but not in HCC or endometrial cancers." (PMID 24708606, 2014).
esophageal cancer (1 paper, 2016). A primary or metastatic malignant neoplasm involving the esophagus. "The esophageal cancer cells were negatively isolated by MACS and subjected to RT-qPCR to detect the expression of circadian clock molecule mRNA, including NFIL3, Per1, Per2, Bmal1, Cry1, Cry2, Clock and Npas2." (PMID 26898709, 2016).
insulinoma (1 paper, 2023). "Circadian expression of clock genes (Clock, Bmal1, Per1,2,3, and Cry1,2) in pancreatic islets and INS1 rat insulinoma cells may indicate that circadian rhythms are generated within the b-cells." (PMID 36768693, 2023).
keloid (1 paper, 2022). An irregularly shaped, elevated mark on the skin caused by deposits of excessive amounts of collagen during wound healing. "Further, with recent single-cell RNA sequencing uncovering four fibroblast subpopulations in normal scars and keloids, it will be interesting to determine miRNA associations with CRY1 and other core clock gene transcripts within each fibroblast subpopulation." (PMID 35445708, 2022).
kidney damage (1 paper, 2023). "Similarly, the pattern of reduction in the expression of metabolism-related genes was not sustained in the ClockΔ19 mice, thus suggesting that the deletion of Cry1 and Cry2 proteins is specifically associated with a metabolic derangement that can contribute to kidney damage." (PMID 37487638, 2023).
liver cancer (1 paper, 2025). An epithelial or non-epithelial malignant neoplasm that arises from the liver. "Cry1 may serve as a potential therapeutic target in liver cancer, as it appears to suppress HCC progression via increased BCL2/BAX ratio to promote apoptosis." (PMID 41142939, 2025).
lung adenocarcinoma (1 paper, 2023). A carcinoma that arises from the lung and is characterized by the presence of malignant glandular epithelial cells. "Survival analysis further revealed that CRY1, CRY2, GPER1, and FBXL3 were negatively related to survival of lung adenocarcinoma patients, while TIM were positively related to survival." (PMID 37924048, 2023).
medulloblastoma (1 paper, 2025). A malignant, invasive embryonal neoplasm arising from the cerebellum. "The gene expression data highlight CRY1 as a defining factor in Group 3 medulloblastoma (MB), particularly in pediatric cases." (PMID 40002179, 2025).
memory impairment (1 paper, 2013). "Memory impairments in Cry mutants are unlikely to result from low attention given that Cry1 and Cry2 mutant mice showed normal object exploration." (PMID 24187535, 2013).
muscular dystrophy (1 paper, 2025). Muscular dystrophy (MD) refers to a group of more than 30 genetic diseases characterized by progressive weakness and degeneration of the skeletal muscles that control movement. "Similarly, Cry1 is downregulated in muscle tissue of a muscular dystrophy mouse model." (PMID 40410591, 2025).
myopia (1 paper, 2026). "Our meta-analysis identified seven novel suggestive loci associated with myopia progression, including FSTL5 on 4q32.2, SMARCA2 on 9p24.3, CCDC3 on 10p13, GALNT6/ACVR1B on 12q13.13, CRY1 on 12q23.3, ULK2 on 17p11.2, and MYL4/EFCAB13-DT on 17q21.32." (PMID 42094695, 2026).
preeclampsia (1 paper, 2022). Preeclampsia is a hypertensive disorder of pregnancy that is characterized by new-onset hypertension with proteinuria presenting after 20 weeks of gestation, and depending on mild or severe forms may initially present with severe headache, visual disturbances, and hyperreflexia. "Further, in our recent study, we found that the placenta from women with preeclampsia presented with increased CRY1 mRNA as well as reduced NR1D2 and PER3 mRNA." (PMID 36712876, 2022).
renal fibrosis (1 paper, 2024). A final common manifestation of a wide variety of chronic kidney diseases characterized by glomerulosclerosis and tubulointerstitial fibrosis. "For example, increasing miR-181a levels can reduce CRY1 expression, activating TLR/NF-κB and potentially improving renal fibrosis in rats." (PMID 38804362, 2024).
retinal degeneration (1 paper, 2025). Degeneration of the retina. "As expected, these include clock genes such as Cry1 and Nfil3 (up) and Per3 and Nr1d2 (down) but also a few other genes, notably linked to retinal degeneration such as Myo7A61 that was substantially downregulated, or Loxl4 and Ppard that were highly upregulated." (PMID 40171795, 2025).
Shock (1 paper, 2021). The state in which profound and widespread reduction of effective tissue perfusion leads first to reversible, and then if prolonged, to irreversible cellular injury. "Additionally, we found that NR1D1, NR1D2, CRY1, CRY2, PER1, PER2 and DBP had altered rhythms in at least some patients with septic shock." (PMID 33900485, 2021).
status epilepticus (1 paper, 2018). Status epilepticus is defined as a continuous seizure lasting more than 30 min, or two or more seizures without full recovery of consciousness between any of them. "In this study, we systematically evaluated the temporal expression of seven core circadian transcripts (Bmal1, Clock, Cry1, Cry2, Per1, Per2, and Per3) and the spontaneous locomotor activity (SLA) in post-status epilepticus (SE) model of mTLE." (PMID 30116220, 2018).
systemic lupus erythematosus (1 paper, 2025). An autoimmune multi-organ disease typically associated with vasculopathy and autoantibody production. "Mice deficient in cry1 and cry2 develop an autoimmune phenotype resembling features of human systemic lupus erythematosus (SLE)." (PMID 41415271, 2025).
temporal lobe epilepsy (1 paper, 2025). A localization-related (focal) form of epilepsy characterized by recurrent seizures that arise from foci within the temporal lobe, most commonly from its mesial aspect. "Meanwhile, in a model of drug-resistant temporal lobe epilepsy, the dysregulation of Cry1, Clock, and Bmal1 was more evident in the hypothalamus and liver, along with Cry1 and Clock diurnal dysregulation in the hippocampus." (PMID 40572688, 2025).
thyroid (1 paper, 2021). "We then chose CLOCK, BMAL1, CRY1, CRY2, PER1 and PER2 to observe the changes of circadian rhythm genes in thyroid malignant tissues." (PMID 34211057, 2021).
ulcerative colitis (1 paper, 2025). An inflammatory bowel disease involving the mucosal surface of the large intestine and rectum. "The core clock gene CRY1 had higher relative expression in IBS (p = 0.031) and ulcerative colitis patients (p = 0.042) compared with control subjects." (PMID 40767289, 2025).
viral infection (1 paper, 2023). "Therefore, we selected BMAL1 and CRY1 for qRT-PCR validation and found that the expression of BMAL1 and CRY1 was significantly downregulated after SVA infection, indicating that after viral infection, piRNAs may exert an effect on circadian rhythm." (PMID 37323834, 2023).